CALR (calreticulin)
Diseases named in the same sentence as CALR in open-access papers (continued):
Sharing a sentence is not in itself a finding about the gene and the disease.
omphalocele (1 paper, 2015). Omphalocele is an embryopathy classified in the group of abdominal celosomias and is characterized by a large hernia of the abdominal wall, centered on the umbilical cord, in which the protruding viscera are protected by a sac. "Interestingly, non-cardiac Pitx2 knockout phenotypes, such as omphalocele, are also present in calreticulin-deficient experimental animal models." (PMID 26179794, 2015).
osteosclerosis (1 paper, 2020). Abnormally high bone density. "Prior to HSCT we documented grade 3 fibrosis and osteosclerosis at bone marrow reevaluation, and mutational analysis of the CALR gene revealed a type 2 mutation." (PMID 31534197, 2020).
ovarian serous cystadenocarcinoma (1 paper, 2021). A malignant serous cystic epithelial neoplasm arising from the ovary. "However, in ovarian serous cystadenocarcinoma (OV) and THCA, higher expression of CALR tends to have better RFS." (PMID 34910788, 2021).
pancreatic adenocarcinoma (1 paper, 2020). "Importantly, calreticulin was further revealed to be closely related to anti‐tumor immunity in pancreatic adenocarcinoma, including multiple immune effector molecules and T‐cell signatures." (PMID 32508042, 2020). "Moreover, calreticulin was observed to be highly expressed in pancreatic adenocarcinoma, and high calreticulin expression significantly favors both overall survival and disease‐free survival of patients with pancreatic adenocarcinoma." (PMID 32508042, 2020).
papilloma (1 paper, 2017). A benign epithelial neoplasm that projects above the surrounding epithelial surface and consists of villous or arborescent outgrowths of fibrovascular stroma. "We show that MmuPV1 challenge of the outbred immunocompetent SKH1 strain produces both transient and persistent papillomas and that vaccination of the mice with a DNA expressing an MmuPV1 E6E7L2 fusion with calreticulin can rapidly clear persistent papillomas." (PMID 28515303, 2017).
Pasteurella multocida infection (1 paper, 2025). "Furthermore, RT-qPCR analysis demonstrated that, compared to the control group, calreticulin mRNA levels in the nasal cavity, trachea, and lung were increased after Pasteurella multocida infection." (PMID 40723838, 2025). "Therefore, investigating whether calreticulin plays a role in the clearance of Pasteurella multocida infection is not only of practical significance for the control of animal diseases but also provides theoretical support for the treatment of human respiratory infections." (PMID 40723838, 2025).
periodontal disease (1 paper, 2024). "On the other hand, regulatory molecules such as microRNAs have also been studied as support in the diagnosis of periodontal disease; one of them is miRNA-1226, which is related to CALR overexpression, protein linked to a decrease in mineralization following the same molecular line." (PMID 39445210, 2024).
polycystic kidney disease (1 paper, 2013). A usually autosomal dominant and less frequently autosomal recessive genetic disorder characterized by the presence of numerous cysts in the kidneys leading to end-stage renal failure. "We demonstrate the value of KUPNetViz by two usage examples: the integration of calreticulin as a key player in a larger interaction network in renal graft rejection and the novel observation of the strong association of interleukin-6 with polycystic kidney disease." (PMID 23883183, 2013).
posttraumatic stress disorder (1 paper, 2020). "A rat model of posttraumatic stress disorder results in increased calreticulin expression and increased ER‐related apoptotic markers, likely through a catecholaminergic mechanism." (PMID 32323496, 2020).
prostate adenocarcinoma (1 paper, 2020). "Additionally, the genetic alteration of CALR also shows significant co‐occurrence with each of all the investigated immune checkpoints in prostate adenocarcinoma." (PMID 32508042, 2020).
protein misfolding disease (1 paper, 2023). "Calreticulin resides in the lumen of the endoplasmic reticulum and performs two main functions, Ca2+ binding and protein chaperoning, a function clearly impaired in CF, a protein misfolding disease." (PMID 37767091, 2023).
reactive lymphoid hyperplasia (1 paper, 2020). "IHC analysis of 26 NKTCL patients and 10 patients with reactive lymphoid hyperplasia (controls) showed that CALR was predominantly localized in the cytoplasm of NKTCL cells." (PMID 33221760, 2020). "Moreover, higher CALR protein expression was detected in a larger proportion of NKTCL patient specimens compared to the reactive lymphoid hyperplasia patient specimens (11/26 vs. 1/10, P = 0.0001)." (PMID 33221760, 2020).
retinal degeneration (1 paper, 2017). Degeneration of the retina.
Sinus bradycardia (1 paper, 2015). Bradycardia related to a mean resting sinus rate of less than 50 beats per minute. "Previous studies have identified sinus bradycardia, complete heart block and sudden death associated with dysregulated CALR expression." (PMID 26179794, 2015).
squamous carcinoma (1 paper, 2009). "In accordance with our results, downregulation of calreticulin has been noted in other squamous cell carcinomas, such as primary laryngeal and maxillar squamous cell carcinoma." (PMID 19367286, 2009).
ST Elevation Myocardial Infarction (1 paper, 2025). A myocardial infarction that produces elevation in the ST segments of the ECG. "We present a case of a 62-year-old male with CALR-mutated ET who developed a non-ST-elevation myocardial infarction (NSTEMI) as the initial manifestation of his disease." (PMID 40278216, 2025).
thromboses (1 paper, 2024). "Conversely, CALR mutation variants were similar in their hemoglobin levels (p = 0.8), leukocyte counts (p = 0.2) and major thromboses at or prior to ET diagnosis (p = 0.2)." (PMID 38238287, 2024). "The number of major thromboses at or prior to diagnosis was significantly higher in JAK2 patients (n = 149, 23%) compared to CALR (n = 16, 9%; p < 0.001) and TN (n = 11, 10%; p = 0.003)." (PMID 38238287, 2024).
triple-negative breast carcinoma (1 paper, 2021). An invasive breast carcinoma which is negative for expression of estrogen receptor (ER), progesterone receptor (PR), and human epidermal growth factor receptor 2 (HER2). "In triple-negative breast cancer patients, down-regulation of CALR and TAPBP tend to indicate a poor prognosis.Previous studies have shown that the carcinogenic mechanism of CALR is related to the exposure of malignant primordial cells to CALR, HSP70 and HSP90 on the plasma membrane." (PMID 34910788, 2021).
tumor (773 papers, 2005 to 2026). "In synergy with immunotherapy, dying tumor cells undergoing ferroptosis or cuproptosis release a series of damage-associated molecular patterns (DAMPs), including ATP, calreticulin (CRT), and high-mobility group box 1 (HMGB1)." (PMID 41201667, 2025). "Radiation therapy is known to induce the production of heat shock proteins, tumor-associated antigens, and calreticulin, which promote dendritic cell maturation, enhance tumor tissue penetration, and trigger immune responses against cancer." (PMID 39558814, 2025). "During ICD, dying tumor cells release tumor-associated antigens along with danger-associated molecular patterns (DAMPs) such as calreticulin, ATP, and high-mobility group box 1 (HMGB1)." (PMID 40677710, 2025). "The soluble ER-associated chaperone calreticulin (CRT) can be more easily translocated to the surface of tumour cells through ROS-mediated ferroptosis." (PMID 41153383, 2025). "Upon induction, ferroptotic tumor cells release damage-associated molecular patterns (DAMPs) such as calreticulin (CRT), ATP, and high-mobility group box 1 (HMGB1), which act as “find-me” and “eat-me” signals to recruit dendritic cells (DCs)." (PMID 40887613, 2025). "When tumor cells are mechanically disrupted, they release unaltered tumor antigens along with molecules such as calreticulin, HMGB1, and ATP, collectively called damage-associated molecular patterns (DAMPs)." (PMID 41458348, 2025). "The antibody targets the C‐terminus novel sequence of all mutant CALR variants in MPN and CD3 on T cells, thus engaging CD8 T cells into killing cells that expose on the cell‐surface the mutated CALR tumour antigen." (PMID 40619749, 2025). "This combination leads to massive cancer cell lysis, releasing tumor-associated antigens and stimulating the translocation of calreticulin to the tumor cell surface." (PMID 40061141, 2025). "Calreticulin exposure on the surface of cells is a hallmark of immunogenic cell death, promoting phagocytosis and adaptive immune responses against tumor cells." (PMID 40943044, 2025). "As a result, the ICD process is characterized by the up-regulation of calreticulin (CRT) from tumor cells, causing dendritic cells (DCs) to recognize CRT, thus promoting antitumor immunity." (PMID 38868091, 2024). "During ICD process, the tumor release signal molecules, known as damage‐associated molecular patterns (DAMPs), including ATP, calreticulin (CRT), and high mobility group box 1 (HMGB‐1)." (PMID 38774917, 2024). "Subsequent to ICD, deceased tumor cells release damage-associated molecular pattern molecules (DAMPs) such as calreticulin (CRT), heat-shock proteins, high-mobility group box 1, and adenosine triphosphate." (PMID 38512518, 2024). "High mobility group box-1 protein (HMGB1), phosphatidylethanolamine, and calreticulin are among damage associated molecular patterns (DAMPs) released by ferroptosis of tumor cells, which encourage DCs maturation and antigen presentation." (PMID 38853203, 2024). "Overall, the correlation between intracellular ICD hallmark genes and tumor-infiltrating immune cells implied an essential role of immunogenic substances, especially CALR, in triggering antitumor immunity." (PMID 36907982, 2023). "During ICD, tumor cells release damage-associated molecular patterns (DAMPs) such as calreticulin on the cell surface, secreted HMGB1, ATP molecules, HSP70, and HSP90." (PMID 38102594, 2023). "CALR has been associated with malignant transformation, tumor progression, and response to cancer therapy." (PMID 37547766, 2023). "The “eat me” signals mainly include tumor-associated antigens generated in response to oncogenic stresses, the ER chaperone protein calreticulin and the glycoprotein SLAMF7." (PMID 36882399, 2023). "Further analysis suggested that ICD hallmark genes, especially CALR, were correlated with tumor-infiltrating immune cells and patient prognosis in EC." (PMID 36907982, 2023).
tumor (continued). "Oncolytic viral therapy relies on tumor cell destruction, which has been shown by multiple labs to result in the release of damage-associated molecular patterns (DAMPs) such as ATP, calreticulin, and HMGB1." (PMID 36789106, 2023). "There is more evidence that CALR is associated with cell carcinogenesis, drug resistance of tumor cells, and epithelial-mesenchymal transformation." (PMID 37275895, 2023). "Anthracycline-induced phosphorylation of eukaryotic translation initiation factor 2A (eIF2α) causes exposure of calreticulin in tumor cells, which acts as an “eat me” signal; thus, DCs phagocytose calreticulin-exposed tumor cells." (PMID 35806328, 2022). "In this context, irradiation causes formation of necrotic tumor areas, characterized by calreticulin overexpression at the cell surface, which stimulates phagocytosis of tumor cells and further antigen release promoting the immune response." (PMID 36544712, 2022). "As an endoplasmic reticulum (ER) marker, when exposed on the tumor cell surface during ICD, CALR promotes the uptake of tumor-specific antigen (TSA), and its mutation compromises immunosurveillance." (PMID 35444934, 2022). "In vivo experiments showed that CH3-R9-RGD@ce6/siP3H4 nanocomposites caused pathological changes, suppressed BC tumor growth, promoted caspase 3 expression, and enhanced calreticulin exposure in tumor cells." (PMID 36297587, 2022). "Upregulated genes included CALR (calreticulin), and several HSPs implicated in tumour immune evasion and critical for maintaining cellular protein homeostasis." (PMID 36220861, 2022). "In particular, eIF2α phosphorylation is required for cell surface exposure of the ER chaperone calreticulin, which facilitates the transfer of tumor-associated antigens to DCs." (PMID 36430552, 2022). "A key characteristic of ICD is the release of danger-associated molecular patterns (DAMPs) by tumor cells, which include ATP, calreticulin (CALR), and high mobility group box 1 (HMGB1)." (PMID 35979349, 2022). "Calreticulin can alter the proliferation of a variety of cell types, and is implicated in tumor growth, tumor suppression, and wound healing." (PMID 35514983, 2022). "This facilitates the evaluation of a possible association between the RT-induced upregulation of calreticulin and the recruitment of immune cell subsets that are in favor of targeting the tumor." (PMID 33920544, 2021). "DAMPs or TAAs released by dying tumor cells caused by radiation include not only immune enhancing elements such as calreticulin and HMGB1 but also immunosuppressive factors such as IL-10 and TGF-β." (PMID 33968889, 2021). "It has been reported that the expression of CALR protein is increased in tumor cells, which is associated to increased cell death in different tumours." (PMID 33996626, 2021). "Docetaxel-based chemotherapy can modulate anti-tumour immune responses inducing calreticulin, a damage-associated molecular patterns associated to the immunogenic cell death." (PMID 32334548, 2020). "After photodynamic treatment, this Fe3O-based nMOF caused tumor cell death effectively through immunogenic cell death, which was investigated by detecting cell surface exposure of calreticulin." (PMID 32355277, 2020). "By following this notion, the data described here implies, that healthy individuals are able to clear cells harboring the CALR-mutation and, accordingly, this tumor cell elimination generates CALR-mutant specific Tmem." (PMID 30655510, 2019). "Our data suggest that increased CALR levels in both primary and metastatic tumor tissues are associated with superior disease outcome linked to the establishment of a tumor microenvironment (TME) exhibiting TH1 polarization and activation of immune effectors." (PMID 31747968, 2019). "Animal calreticulin is linked with the recognition of tumor and apoptotic cells, and wound healing in plants it is linked to growth and stress responses." (PMID 31430995, 2019).
tumor (continued). "Proton radiation and photon radiation upregulate surface cell molecules, such as ICAM1, HLA, the tumor-associated antigens MUC-1 and CEA, and calreticulin, to comparable extents, increasing the killing of tumor tissue by T cells." (PMID 30487462, 2018). "In particular, the death of tumor cells can lead to the release of several danger-associated molecular pattern molecules (DAMPs) such as calreticulin which in turn activates innate and adaptive immune cells." (PMID 29245952, 2017). "After establishment of the LMP1-expressing tumor model, we designed a calreticulin conjugated DNA vaccine that encoded full-length LMP1 (LMP1/pcDNA3.1)." (PMID 28056887, 2017). "NAC, in particular anthracyclines and taxanes, is known to disrupt tumour cells, exposing expression of calreticulin and release of tumour-associated antigens (TAAs)." (PMID 28913366, 2017). "Tumours with high miR-27a, low calreticulin and CD8+ T cells' infiltration were associated with distant metastasis and poor prognosis." (PMID 26913609, 2016). "Taken together, in clinical settings, calreticulin and associated chaperones can be exposed on tumor cells or in serum from patients." (PMID 25688334, 2015). "In the protocols for PDT of tumors in situ, the therapeutic gain seen with adjuvant calreticulin can be expected to result from the association of this protein with cancer cells upon its administration by tumor-localized injection." (PMID 25692097, 2015). "Our preclinical data indicate that alternating electric fields stress the cytoplasm of dividing tumor cells and that cause the translocation of calreticulin from the endoplasmic reticulum to the surface of cell membrane 25,26." (PMID 24574359, 2014). "For example, anthracyclin treatment of tumor cells causes apoptosis that leads to exposure of calreticulin on the surface, which acts as a signal to induce phagocytosis and promote anti-tumor T cell responses in vivo." (PMID 23226685, 2012). "CALR is a highly conserved chaperone protein that resides primarily in the endoplasmic reticulum and is associated with various biological processes, among them, tumor calcification, cell adhesion, and immune response." (PMID 40557150, 2025). "Damage-associated molecular patterns such as calreticulin, high mobility group box 1 and ATP act as danger signals during tumor cell death, with calreticulin serving as an “eat me” signal for antigen-presenting cells and ATP as a “find me” signal for monocyte recruitment." (PMID 41471095, 2025). "Some of the DAMPS associated with tumor immunity are calreticulin, extracellular ATP, and high-mobility group box 1 protein (HMGB1), which favor DC maturation and priming of protective T-cell responses that can kill tumor cells and establish anti-tumor immunological memory." (PMID 39456655, 2024). "Refining the analysis for specific genes and cancer types revealed that two genes from the antigen presentation pathway (that is, B2M and CALR) displayed recurrent patterns of inactivating mutations and focal biallelic deletions across several tumor types, as well as in the pan-cancer cohorts." (PMID 37165135, 2023). "Moreover, we identified an unreported correlation between a reduction of Arginase‐1+ bone marrow cells and the presence of CALR mutations, linking tumor‐promoting immunity and molecular drivers." (PMID 36524315, 2023). "For example, anthracyclines and oncolytic viruses induce immunogenic cell death (ICD) in which dying tumor cells release or express danger-associated molecular patterns (DAMPs) such as calreticulin (CRT), High Mobility Group Box-1 (HMGB-1), and heat shock proteins (HSP-70 and HSP-90)." (PMID 37370701, 2023). "Immunogenic cancer cell death induced by PDT starts with the release of specific molecular patterns associated with tumor damage and generates anti-tumor immunity based on surface calreticulin, heat shock protein 70, secreted adenosine triphosphate, and high-mobility group box 1 protein." (PMID 37762000, 2023).